KLF6 (KLF transcription factor 6)
Diseases named in the same sentence as KLF6 in open-access papers (continued):
Sharing a sentence is not in itself a finding about the gene and the disease.
tumor (continued). "Finally, in vitro assays demonstrated that inhibition of ZFAS1 reduced CC tumor growth and the expression levels of KLF6, but increased the expression levels of miR-190a-3p." (PMID 35112985, 2022). "Of course, there are still many unknown mechanisms of the tumor suppressor function of KLF6, which need to be further explored by researchers in the future." (PMID 33816511, 2021). "Accumulative evidence has demonstrated the tumor-suppressing function of KLF6 in various tumors." (PMID 33431838, 2021). "As expected, the expression of KLF6 was lower in tumor tissues than that in normal tissues." (PMID 33431838, 2021). "KLF6 was proved to impede macrophages M2 polarization and M2 macrophages-mediated tumor metastasis." (PMID 34078414, 2021). "When KLF6 is abnormally expressed in tumors, it leads to down-regulation of the downstream gene p21 expression, which hinders the apoptotic process of tumor cells and is in a state of malignant proliferation, leading to continuous development of tumor cells." (PMID 33955459, 2021). "Mechanistic study revealed that SNHG6 could recruit EZH2 and maintain high level of H3K27me3 to repress the transcription of tumor-suppressor genes, including KLF6." (PMID 33431838, 2021). "By contrast, KLF2, KLF4 and KLF6 are more likely tumor suppressors in different cancers." (PMID 32523679, 2020). "Besides, KLF6 also suppresses cell migration and tumor metastasis in an E-cadherin-independent manner." (PMID 32733026, 2020). "Thus, one possibility is to reintroduce or upregulate the expression of tumour-suppressive full-length KLF6 in these cancer types." (PMID 32998281, 2020). "KLF6 directly activates E-cadherin transcription to inhibit tumor invasion and metastasis." (PMID 32733026, 2020). "Furthermore, in both normal and tumor contexts, KLF6 is required for oxidative and oncogene-induced cellular senescence." (PMID 32581828, 2020). "Moreover, tumours of miR‐513a‐5p antagonists groups presented higher positive rate of KLF6 compared with NC antagonist groups." (PMID 33460239, 2020). "Moreover, tumours of sh‐MIR4435‐2HG+pcDNA3.1‐KLF6 groups presented higher positive rate of KLF6 compared with sh‐MIR4435‐2HG+pcDNA3.1 groups." (PMID 33460239, 2020). "MIR4435‐2HG knockdown caused less tumour formation and significantly decreased tumour size compared with sh‐NC+pcDNA3.1 group, whereas results demonstrated that the effect of MIR4435‐2HG knockdown on tumour growth was reversed by KLF6 overexpression." (PMID 33460239, 2020). "KLF6 is a tumor suppressor, while KLF8 functions as an oncogene in CRC." (PMID 32523679, 2020). "KLF6 function in the regulation of tumor growth has been validated through several approaches." (PMID 31824948, 2019). "However, in cultured human podocytes, KLF6 knockdown resulted in activation of the intrinsic apoptotic pathway, which suggested that the function of KLF6 in normal cells is opposite to that in RB tumor cells." (PMID 31723124, 2019). "Moreover, KLF6-expressing GBMs often express a dominant-negative splice variant (KLF6-SV1), which is mislocalized to the cytoplasm and antagonizes the tumor suppressor activity of the full-length KLF6 protein (KLF6-FL)." (PMID 31861467, 2019). "KLF6-targeted cells formed smaller tumours when compared to control cells." (PMID 30858363, 2019). "Regarding its role in tumorigenesis, KLF6 is considered a tumor suppressor." (PMID 31824948, 2019). "Indeed, many studies pointed the function of KLF6 as a tumor suppressor because of its ability to reduce cell proliferation through several biochemical mechanisms including regulation of cell cycle, oncogenic products, and apoptosis." (PMID 29854578, 2018). "For instance, SP1 and KLF6 are known tumor suppressors in colorectal cancer." (PMID 28684851, 2017).
tumor (continued). "Therefore we proposed that platelet-derived TGF-β was involved in tumor growth and affected KLF6 expression." (PMID 29152072, 2017). "Kruppel-like factor 6 (KLF6) is a tumour-suppressing protein." (PMID 28881705, 2017). "However, reducing KLF6 expressionin SMMC.7721 cells abrogated the tumor cell growth induced by platelets and their releasates." (PMID 28638139, 2017). "Although the tumor-suppressing activity of the KLF6 gene is well known, it has not been reported whether natural nutrients such as anthocyanins could affect KLF6 expression." (PMID 27690088, 2016). "This study could be the first report that KLF6 can be up-regulated by anthocyanin C3G extracted from Chinese bayberry, thus reducing the mouse tumor growth burden." (PMID 27690088, 2016). "Using an orthotopic HCC model in nude mice, the negative control and KLF6/basigin-2 mice showed the apparent presence of GFP fluorescence emitted from primary tumor, whereas mice with KLF6 overexpression exhibited a lower GFP fluorescence signal at the observation endpoint." (PMID 27057625, 2016). "In this study, it was first discovered that C3G, a major component of anthocyanins from Chinese bayberry, could suppress the growth of SGC-7901 tumor xenografts through up-regulating KLF6 gene expression." (PMID 27690088, 2016). "KLF6 promotes tissue remodeling due to its ability to activate genes that are members of the TGF-β signaling pathway, which are implicated in vascular remodeling, tumor metastasis and apoptosis." (PMID 24397367, 2014). "In conclusion, we demonstrated that the overexpression of PTTG1 could be repressed by KLF6 tumor suppressor through the activation of PKC/ERK signaling in myeloid cell differentiation." (PMID 23977008, 2013). "Furthermore, the PMA-responsive region that we identified is located at nucleotides −406 to −246 upstream of the PTTG1 promoter and contains a binding site for KLF6, which is a zinc-finger transcription factor with tumor suppressor function." (PMID 23977008, 2013). "On the other hand, it has been reported that KLF6 has the ability to reduce cell proliferation rate through increased c-Jun degradation by the proteasome dependent pathway upon tumor promoter and proliferating cell signaling generated by phorbol 12-myristate 13-acetate and ionomycin." (PMID 20126619, 2010). "Also the sub-cellular distribution of KLF6 was confined to the cytoplasm compartment in tumor tissues in contrast with a uniform nuclear and cytoplasmic distribution for each histological normal counterpart." (PMID 20126619, 2010). "Thus, differential regulation of KLF6 under specific cell environment provides a plausible explanation on the divergent information published so far about the tumor suppressor function of KLF6." (PMID 20126619, 2010). "Similar KLF6 distribution was detected in a different lot of tumor tissue microarrays (L2a–c)." (PMID 20126619, 2010). "Moreover, within the tumor population expressing nuclear KLF6, it was found that seventy-five percent (21/28) of the cases overexpressed ERBB2." (PMID 20126619, 2010). "Given KLF6's tumor suppressor function and KLF6-SV1's oncogenic/anti-apoptotic function, this finding may have broad implications." (PMID 20844588, 2010). "Moreover, the nude mouse subcutaneous tumor model indicated that KLF6 overexpression could rescue the decrease in 5-FU resistance in HCT15-FR cells induced by C646." (PMID 40082673, 2025). "Moreover, a nude mouse subcutaneous tumor model indicated that SEMA3C overexpression could rescue the decrease in 5-FU resistance in HCT15-FR cells induced by KLF6 knockdown." (PMID 40082673, 2025). "We further explored whether LCACs exert their anti-tumor effect through KLF6." (PMID 40370557, 2025). "In addition, KLF6 has been reported to be a tumor inhibitor in several cancer kinds." (PMID 36605481, 2023). "Interestingly, increased UHRF1 epigenetically suppresses tumor KLF6 expression." (PMID 35664070, 2022).
tumor (continued). "Moreover, KLF6 is also increasingly appreciated for its tumor suppressor function." (PMID 33816511, 2021). "In addition, KLF6 silencing attenuates ART-mediated inhibition of tumor growth in vivo." (PMID 31723124, 2019). "Furthermore, TUNEL assay showed that KLF6 silencing could attenuate the tumor cells apoptosis rate following ART treatment." (PMID 31723124, 2019). "Therefore, we hypothesized that the effects of platelets on tumor cells are attributable to the ability of decreasing tumor cell expression of KLF6." (PMID 28638139, 2017). "Thus, KLF6 is likely the main factor responsible for platelet releasates-mediated tumor growth." (PMID 28638139, 2017). "Therefore, we hypothesized that the pro-proliferative effects of platelets on tumor cells are attributed to the ability of platelet-derived TGF-β to decrease the expression of KLF6 in tumor cells." (PMID 29152072, 2017). "Next, we examined whether KLF6-wt and KLF6-sv1 affected tumor formation in vivo." (PMID 28166199, 2017). "We next determined whether KLF6 overexpression could suppress tumor growth and metastasis in vivo." (PMID 27057625, 2016). "However, cell context and/or biochemical signaling, interaction with specific transcriptional partners and/or sub-cellular distribution of KLF6 could manage the outcome of KLF6 function to different and opposite tumor pathways." (PMID 20126619, 2010). "Thus, KLF6 tumor suppressor could represent a new molecular marker candidate for tumor prognosis and/or a potential target for therapy strategies." (PMID 20126619, 2010). "Interestingly, KLF6 splicing correlates with tumor stage and survival, and may be useful as a prognostic factor." (PMID 20119532, 2009). "However, deregulation of KLF6 stability following ubiquitination may alter its tumor suppressor function in UV-B irradiated cell lines." (PMID 20119532, 2009). "Consistently, in tumor tissues of DEN/CCl4 mice, treatment with LCAC-16:0 enhanced KLF6 expression as well." (PMID 40370557, 2025). "A comparison of EGR1, FOS, IER2, JUN, KLF6, MYC, and FOSL2 gene expression in 481 tumor samples revealed that individual tumors vary substantially in the expression of all analyzed genes." (PMID 39436655, 2024). "Cluster 0 expressed several tumour-related transcription factors such as ELK4, CREB1, cJun, JunD, KLF6, ETS-1 and ZNF217." (PMID 38480935, 2024). "The top-ranking genes included those that contribute to tumor development and drug resistance, such as AKT1, KLF6, and NCOR2." (PMID 37568192, 2023). "To determine the protein levels of KLF6 and SGMS2, we obtained nine pairs of LUSC tumor and normal samples from patients for IHC staining." (PMID 36056909, 2023). "Compared to para-tumor specimens, the mRNA levels of KLF5, KLF7, KLF8, and KLF13 were elevated, whereas those of KLF4, KLF6, and KLF10 were reduced in HCC specimens." (PMID 37554278, 2023). "Most genes considered tumor specific in previous studies (tumor suppressor genes: SOCA3, KLF6, and PTGDS; tumor enhancer genes: SLC38A2, DUSP1, and FGF7) were expressed predominantly in tumor stroma or remission stroma than that in pre-treatment tumors." (PMID 36505794, 2022). "Although KLF6 and CSF1 are differentially regulated by UHRF1, their regulatory mechanisms are functionally orchestrated to help UHRF1 fulfill its tumor-promoting roles in the course of HCC progression." (PMID 35664070, 2022). "We observed an additional tumour with integration in KLF14 located in 7q32.3, one in KLF4 located in 9q31.2, and one in KLF6 located in 10p15.1." (PMID 35398964, 2022).
tumor (continued). "Previous work has shown that miR-543 plays a role in proliferation of C2C12 cells via targeting Krüppel-like factor 6 (KLF-6), which is a suppressor of multiple tumor cells." (PMID 36091396, 2022). "In vivo experiments further validated that lnc-KASRT enhanced tumor growth and reduced tumor apoptosis; meanwhile, it also increased tumor KLF6-SV1, MMP-1, and MMP-9 expressions but decreased tumor SRSF1 and KLF6-WT expressions in xenograft mice." (PMID 34568030, 2021). "It has been reported that KLF5, KLF6-SV, KLF4α and KLF7 have a role in tumor progression, epithelial to mesenchymal transition (EMT) and metastasis, whereas KLF2, KLF6, KLF4 and KLF15 inhibit proliferation, metastasis and cell cycle in BC." (PMID 32796696, 2020). "Whilst the full-length KLF6 is established as a tumour suppressor in many cancer types, KLF6-SV1 is deemed to be pro-oncogenic by antagonising the full-length KLF6 functions in a dominant-negative manner." (PMID 32998281, 2020). "The change in tumor weights also showed that ART treatment significantly inhibited tumor growth and that KLF6 silencing attenuated the effect of ART (NC: 0.31 ± 0.06 g, ART + LV-Ctrl: 0.09 ± 0.04 g, and ART + LV-shKLF6: 0.16 ± 0.06 g)." (PMID 31723124, 2019). "We injected pools of 786-M1A and OS-LM1 cells in which KLF6 had been targeted using CRISPR-Cas9 subcutaneously into immunocompromised mice and followed tumour formation and growth over time." (PMID 30858363, 2019). "Krüppel-like factor 6 (KLF6) is a ubiquitously expressed zinc finger transcription factor and has been characterized as a tumor suppressor gene that mediates growth suppression in a variety of human cancers." (PMID 29152072, 2017). "We first measured KLF6, Sp1 and basigin-2 expression levels in HCC tumor tissues compared with normal liver tissues, and HCC cell lines." (PMID 27057625, 2016). "For example, KLF family proteins have been shown to have either a tumor-promoting (KLF4, KLF6, KLF9, KLF10, KLF11, and KLF17) or a tumor-suppressing (KLF5, KLF12) role by intervening in cell signaling associated with proliferation and/or suppression." (PMID 26320172, 2015). "Hence, it is still not fully settled whether the tumor suppressor function of KLF6 is directly associated with its ability to regulate target genes." (PMID 20126619, 2010). "In contrast, CD8 effector cells exhibited downregulation of multiple key genes involved in tumor-suppressive transcriptional regulation (HIST1H1C, ZNF331, KLF6, and BTG1) and immune activation and trafficking (CXCR4, CD69, and TNFAIP3) in LS carriers, which was more severe in LS-CRC." (PMID 40909768, 2025). "The overexpression of KLF6 has negative effects on tumor growth and progression; the silence of KLF6 leads to the increase of tumorigenicity." (PMID 37405258, 2023). "Whereas for the SP1, KLF6, and KLF2, discordant findings have been reported as to whether they play a tumor-promoting or suppressing role in HCC progression." (PMID 36902112, 2023). "Overexpression of KLF6 reduced cell proliferation and decreased cell invasive potential by reducing the expression of PCNA and MMP-9 in HCC cells, eventually leading to suppression of tumor growth in vivo." (PMID 36902112, 2023). "In an earlier study, it was shown that KLF6 expression is lost in cancerous tissues obtained from HCC patients and HCC cell lines (HepG2 and Hep3B), suggesting that it may act as a tumor suppressor in liver carcinogenesis." (PMID 36902112, 2023). "Another tumor suppressor, Krueppel-like factor 6 (KLF6), which works as a negative NF-κB regulator and contributes to NF-κB activation in GBM, is lost." (PMID 38201528, 2023). "IHC analysis showed that KLF6 protein was expressed more in the tumor tissue than the normal tissue, which is consistent with RNA‐seq analysis." (PMID 36056909, 2023). "One study correlated overexpression of alternative splice isoforms of KLF6, without KLF6 mutation, with PDAC tumor grade and survival." (PMID 37239940, 2023).
tumor (continued). "Knockdown of the tumor-suppressive coding gene KLF6 did not affect CENP-C levels, suggesting that mRNAs do not recruit CENP-A." (PMID 35235361, 2022). "Notably, miR-148a is a member of the miR-148/152 family, and acts as a tumor suppressor in a variety of human solid tumors and participates in biological functions by targeting mature mRNAs, including WNT-1, Bcl-2, and KLF6." (PMID 35892859, 2022). "Furthermore, some oncogenic genes like EGFR, CDK6, YAP1, and MMP7 were amplified in the TP53INP2-low patients while some tumor suppressor genes including CDKN2A, KLF6, and PTEN were deleted." (PMID 33897760, 2021). "MiR-200c-3p potentially played a tumor-promoting role in the occurrence and development of GCC, which may be achieved by targeting KLF6." (PMID 34524611, 2021). "Their results showed that the action of KLF6 and KLF6-SV1 on E-cadherin could affect tumor invasion." (PMID 33816511, 2021). "Consistently, the clinical correlation between the expression of EZH2, KLF-6, Sp-1, and SNHG6 in patient tumor samples also showed that both EZH2 and Sp-1 displayed the positive correlation with SNHG6, whereas KLF6 and p21 exhibited the negative correlation with SNHG6." (PMID 33431838, 2021). "KLF6 functional interrogations revealed that KLF6 overexpression had negative effects on tumour growth and progression, whereby KLF6 silencing resulted in increased tumorigenicity." (PMID 32998281, 2020). "In addition, Kruppel-like Factor 6 (KLF6); a tumour suppressor through regulation of the p21Cip1 cyclin-dependent kinase inhibitor, has been identified as a novel DNA-binding partner of AhR to express inducible-TCDD when bound at the non-consensus XRE." (PMID 32456012, 2020). "Moreover, bioinformatics and luciferase reporter assay confirmed that miR-181a-5p targeted the 3′-UTR region of KLF6 and KLF15 mRNA, which were two tumor suppressor genes." (PMID 32998707, 2020). "There are a further eight tumor-suppressor genes (DLEU2, CDKN2C, SPRY4, UBE2QL1, LIN9, TFPI2, LRIG3, DUSP1) and six genes serve as both oncogenes and tumor-suppressor genes (FOXO1, CAV1, KLF6, CDK6, PLK1, CTGF)." (PMID 30563222, 2018). "Taken together, these data clearly demonstrate that the pro-proliferative effect of platelets on HCC cells is mediated by KLF6 and independent of a direct interaction between platelets and tumor cells." (PMID 28638139, 2017). "The identification of KLF6 as an important regulator of HCC cell migration and invasion emphasizes an essential role of this tumor suppressor gene in mediating HCC oncogenesis and tumor behavior." (PMID 27057625, 2016). "It is also unclear how the increase in KLF6 and JUN gene products in response to hypoxia influences cancer phenotypes, as KLF6 and JUN are known to act as oncogenes or tumor suppressors depending on various factors, such as cell type and stimuli derived from different cellular environments." (PMID 26703734, 2015). "Six genes, RPL13A, KLF6, LOC100129599, GBE1, PDGFA, and UHRF1 were altered in lymph node metastases of both cell lines relative the primary tumor, suggesting they may represent changes important for metastatic growth in lymph nodes." (PMID 23118918, 2012). "Our results from RNA-seq with the in vitro and in vivo findings suggested that CBD might induce the expression of DUSP1 and KLF6, following the HNSCC tumor suppression via the DUSP1 and/or KLF6 dependent activation of apoptosis and autophagy cellular signaling on HNSCC." (PMID 33244087, 2020). "Similarly, this effect of platelets on KLF6 expression was independent of direct contact between platelets and tumor cells because pellets of CRP-activated platelets did not affect the expression of KLF6 in HCC cells." (PMID 28638139, 2017).